PTP4A3 (protein tyrosine phosphatase 4A3)
Diseases named in the same sentence as PTP4A3 in open-access papers (continued):
Sharing a sentence is not in itself a finding about the gene and the disease.
diabetes (1 paper, 2022). "Accordingly, ISG15 and PTP4A3 may interact with STAT1 to affect diabetes and IA, though more studies are needed." (PMID 36561297, 2022). "In diabetes and IA, ISG15 was upregulated as a co-interacting protein of STAT1, while PTP4A3 was downregulated as a co-interacting protein of STAT1." (PMID 36561297, 2022).
gynecological cancer (1 paper, 2021). "Our current results complement previous reports and demonstrate that high PTP4A3 expression is common in many cancer cell lines including OvCa, which in the USA is the most fatal gynecological cancer and the fifth most common cancer-related cause of death in women." (PMID 34209460, 2021).
head and neck squamous cell carcinoma (1 paper, 2021). A squamous cell carcinoma that arises from any of the following anatomic sites: lip and oral cavity, nasal cavity, paranasal sinuses, pharynx, larynx, and salivary glands. "Notably, PTP4A3 expression was significantly higher in head and neck squamous cell carcinoma (HNSC) HPV-positive cancer tissues compared with HNSC HPV-negative cancer tissues." (PMID 34630392, 2021).
invasive breast carcinoma (1 paper, 2016). A carcinoma that infiltrates the breast parenchyma. "The highest ranking hit from our screen, PTP4A3 (encoding PRL-3), was amplified or up regulated in approximately 8-16% of all invasive breast cancers between two TCGA datasets." (PMID 26909599, 2016).
kidney cancer (1 paper, 2021). Primary or metastatic malignant neoplasm involving the kidney. "In our validation cohort, PTP4A3 expression is significantly elevated in the tumor tissues by the immunohistochemical staining of PTP4A3 in 49 kidney cancers and 6 normal tissues." (PMID 34630392, 2021). "Few reports have examined the role of PTP4A3 in kidney cancer, and this research has mostly focused on the correlation of clinicopathological characteristics and prognosis." (PMID 34630392, 2021). "To further explore the mechanism of PTP4A3 in RCC, we stained the PTP4A3 in the kidney cancer tissue array which containing 5 different tumor histological subtypes and 6 kidney normal tissues." (PMID 34630392, 2021).
kidney tumor (1 paper, 2021). "PTP4A3 expression is obviously higher in the kidney tumor tissues (n=49) compare with the normal tissues (n=6) (P=0.028)." (PMID 34630392, 2021).
Lassa fever (1 paper, 2021). A viral hemorrhagic fever that is caused by the Lassa virus, which is transmitted by contact with infected rodents; it is characterized by fever, headache, malaise, myalgia, and hearing loss. "Indeed, we identified several genes for which the expression correlated with infectious status, such as NFE2, PTP4A3, KCNG2, and a substantial number of genes for which the expression is associated with Lassa fever outcome." (PMID 33398113, 2021).
lentivirus infection (1 paper, 2021). Virus diseases caused by the Lentivirus genus. "We utilized the lentivirus infection to ectopic expression of PTP4A3 in 786-O and Caki-2 cell lines." (PMID 34630392, 2021).
muscular dystrophy (1 paper, 2021). Muscular dystrophy (MD) refers to a group of more than 30 genetic diseases characterized by progressive weakness and degeneration of the skeletal muscles that control movement. "Upregulated in both datasets was Tbc1d12 involved in increasing glucose uptake, whereas the shared downregulated genes included Ptp4a3, the downregulation of which increases expression of ECM genes, and Fbxo40, the downregulation of which has been observed in muscular dystrophy." (PMID 34502375, 2021).
ovarian tumor (1 paper, 2018). "We observed elevated levels of PTP4A3 phosphatase in 79% of human ovarian tumor samples, with significant overexpression in tumor endothelium and pericytes." (PMID 29492190, 2018).
periodontitis (1 paper, 2025). An acute or chronic inflammatory process that affects the tissues that surround and support the teeth. "Among them, HLA-C (IVW, nine SNPs, p=0.03) was identified as a risk factor for periodontitis, while STAP1 (IVW, four SNPs, p=0.01) and PTP4A3 (IVW, 10 SNPs, p=0.04) were recognized as protective factors." (PMID 40692979, 2025). "Further investigation revealed that key genes, including human leukocyte antigen C (HLA-C), STAP1, PTP4A3, NEU1, IGLV1-44, IGLL5, and NIPAL4, play critical roles in the pathogenesis of periodontitis." (PMID 40692979, 2025).
poisoning (1 paper, 2020). A condition or physical state produced by the ingestion, injection, inhalation of or exposure to a deleterious agent. "In summary, HIF-1alpha may regulate PTP4A3 to be involved in benzene hematopoietic poisoning progression." (PMID 32024182, 2020).
renal carcinoma (1 paper, 2021). A carcinoma arising from the epithelium of the renal parenchyma or the renal pelvis. "The association of PTP4A3 expression with B cells, CD8+ T cells, CD4+T cells and neutrophil infiltration was confirmed in renal cancer using the GEPIA and TIMER databases." (PMID 34630392, 2021). "We are confidence in our results base on the various online datasets, therefore we are working on the collection of renal cancer samples and focusing on the immune-related role of PTP4A3 in renal cancer." (PMID 34630392, 2021). "Consistent with the unique immune gene profiles of renal cancer subtypes, the correlation of PTP4A3 expression with immune cell infiltration was distinct in KIRP and KIRC." (PMID 34630392, 2021). "This study offers new insights into the function of PTP4A3 in renal cancer and proposes a mechanism for PTP4A3 regulating tumor infiltration of immune cells." (PMID 34630392, 2021). "PTP4A3 plays an important role in the tumorigenesis and metastasis of multiple tumors, but its prognostic role in renal cancer is not well understood." (PMID 34630392, 2021). "Consistent with previous findings, PTP4A3 expression was elevated in many tumor types compared with normal tissues, including renal cancer." (PMID 34630392, 2021). "Together, these findings confirmed the relationship of PTP4A3 to immune cell infiltration and CD79A, CSF1R, INOS, COX2, STAT5A, FOXP3 and CCR8 in KIRP, suggesting an important immune regulation role of PTP4A3 in the renal cancer microenvironment." (PMID 34630392, 2021). "This study is the first reported association of PTP4A3 and PD1 in renal cancer." (PMID 34630392, 2021). "Therefore, PTP4A3 associated with low CD3+/CD8+TILs and indicated poor prognosis in in renal cancers." (PMID 34630392, 2021). "In conclusion, PTP4A3 may be a regulator in the tumor immune microenvironment and a useful biomarker for predicting prognosis and immunotherapy response in renal cancer." (PMID 34630392, 2021). "As there is no study showing PTP4A3 expression and its potential roles in renal cancer, further experiments were conducted to evaluate whether PTP4A3 play as an oncogene in RCC." (PMID 34630392, 2021). "The mechanism of how PTP4A3 regulates immune cells and its impact on renal cancer prognosis remains unclear." (PMID 34630392, 2021). "In the future work, the relationship between PTP4A3 expression and B cells and other T cells including CD4+ T cells, CD45RO+ memory T cells, regulatory T cell need to be explored in renal cancer." (PMID 34630392, 2021). "Immunohistochemical staining indicated that the expression of PTP4A3 associates with CD3+ (P =0.037)/CD8+ (P =0.037) intratumor TILs, not with invasive margins in renal cancer." (PMID 34630392, 2021). "Correlations were observed between PTP4A3 expression and M1 macrophage immune markers such as INOS and COX2 in both KIRP and KIRC, suggesting that PTP4A3 may regulate the polarization of M1 macrophages in renal cancer." (PMID 34630392, 2021). "However, we did not assess whether the combination of PTP4A3 and CD3+ and CD8+ T cells have independent prognostic significance in renal cancer." (PMID 34630392, 2021).
renal cell carcinoma (1 paper, 2021). "In this study, the role of PTP4A3 in renal cell carcinoma immune microenvironments was explored using online databases, including the Oncomine, TCGA, GEPIA, TIMER and Progscan databases." (PMID 34630392, 2021). "PTP4A3 expression and clinical clinicopathological features in the renal cell carcinoma." (PMID 34630392, 2021).
squamous cell lung carcinoma (1 paper, 2021). A carcinoma arising from squamous bronchial epithelial cells. "However, PTP4A3 expression was significantly lower in urothelial carcinoma (BLCA), and squamous cell lung carcinoma (LUSC) compared with normal tissues." (PMID 34630392, 2021).
virus infection (1 paper, 2013). "PTP4A3/PRL-3 mRNA was significantly correlated with virus infection (P = 0.0422), serum AFP (P = 0.0047), PIVKA-II (P = 0.0259), portal vein invasion (P = 0.0156), and vascular invasion (P = 0.0192)." (PMID 23064776, 2013).
cancer (45 papers, 2011 to 2025). A tumor composed of atypical neoplastic, often pleomorphic cells that invade other tissues. "The role of PTP4A3 associated with cell invasion and cancer metastasis has been extensively studied in other cancers but has seldom been reported in BC." (PMID 37304008, 2022). "The loss of signaling by TGFβ during cancer progression causes the activation of the cell survival pathway PI3K/AKT mediated by PTP4A3, which can selectively promote metastasis." (PMID 33498521, 2021). "The genes assayed were neuroendocrine-associated genes (INSM1, ASCL1, NRCAM, and SNAP25), one gene centered in the gene regulatory network (NUF2), and five possibly cancer-associated genes (PTP4A3, RFC4, REST, APEH, and FBLN2)." (PMID 34395507, 2021). "It is noteworthy that PTP4A3 has been reported to be induced by genotoxic stress caused by cancer chemotherapeutic agents such as cisplatin, etoposide and doxorubicin." (PMID 34209460, 2021). "Phosphatases of regenerating liver (PRLs), PRL-1, PRL-2, and PRL-3, constitute a group of three dual specificity phosphatases encoded by the genes PTP4A1, PTP4A2, and PTP4A3, respectively, and whose high expression is associated to cancer progression." (PMID 33425892, 2020). "Although Ptp4a3 is normally associated with late-stage cancer and metastasis, we observed increased Ptp4a3 expression in the colon of wildtype mice immediately following treatment with the carcinogen azoxymethane." (PMID 23555575, 2013). "Moreover, tumors derived from Ptp4a3-null mice overexpresssed the cancer associated IGF1Rβ and c-MYC suggesting involvement of these oncogenic signaling pathways." (PMID 23555575, 2013). "During cancer, PTP4A3 transcriptional upregulation of mRNA correlates with advanced stage and poor prognosis." (PMID 40657934, 2025). "Given both the paradoxical role of autophagy in cancer and PTP4A3 protein overexpression promoting autophagy to enhance tumour cell growth, the autophagy status of HGSOC cells was examined." (PMID 40657934, 2025). "Several substrates of PTP4A3 have been reported, including FZR1, Keratin 8, Integrin β1, and Leo l, where the phosphorylation levels of the substrates are regulated by PTP4A3, thereby affecting cancer-related signaling pathways and cancer progression." (PMID 38611852, 2024). "It has been previously reported that PTP4A3 plays a variety of roles in the process of cancer metastasis." (PMID 36213837, 2022). "We investigated differential PTP4A3 mRNA levels in tumor and normal tissues across various cancer types in the Oncomine database." (PMID 34630392, 2021). "Phosphatase of regenerating liver-3 (PRL-3/PTP4A3) is upregulated in multiple cancers, including BCR-ABL1- and ETV6-RUNX-positive acute lymphoblastic leukemia (ALL)." (PMID 29423065, 2018). "Elevated PTP4A3 expression has also been correlated with poor patient prognosis and metastatic processes in several cancer types." (PMID 29492190, 2018). "Phosphatases of regenerating liver (PRLs) comprise a group of 3 highly homologous small DSPs (PRL-1/PTP4A1, PRL-2/PTP4A2, and PRL-3/PTP4A3) overexpressed in several cancer types, including hematological malignancies." (PMID 30515156, 2018). "Ptp4a3 is located in chr8q24, which is one of the most commonly amplified chromosomal regions in human cancers, including OvCa, suggesting a fundamental role in tumor maintenance or dissemination." (PMID 29492190, 2018). "PTP4A1 and PTP4A3 have been reported to promote activation of Rho and of its major effector Rho-associated protein kinase (ROCK) in cancer cells." (PMID 29057934, 2017). "It is likely that this event contributes to elevated Ptp4a3 gene expression in cancer through SMAD3/4 inactivation." (PMID 23555575, 2013). "Protein tyrosine phosphatase type IVA member 3 (PTP4A3/PRL-3), a metastasis-associated phosphatase, plays multiple roles in cancer metastasis." (PMID 23064776, 2013).
cancer (continued). "The expression of PTP4A3/PRL-3 protein was also correlated with advanced cancer stages (P < 0.01); this resulted in a significantly poorer prognosis in both overall (P = 0.0024) and recurrence-free survival (P = 0.0227)." (PMID 23064776, 2013). "PTP4A3 protein expression is upregulated in multiple human cancers, including OC." (PMID 40657934, 2025). "Although the involvement of PTP4A3 in diseases other than cancer remains largely unexplored, it has also been identified as a potential protein biomarker and therapeutic target in Alzheimer's disease, implicated in a contributory role in the disruption of the blood–brain barrier." (PMID 40657934, 2025). "The data obtained revealed that with the exclusion of PTP4A3 and GGCT, and the levels of TTEP expressions were significantly (p < 0.05) associated with the resistance of cancer cell lines to several classes of small molecules of anti-cancer functions." (PMID 35990603, 2022). "A direct target of TGFβ signaling that has been inhibited in cancer treatment is PTP4A3." (PMID 33498521, 2021). "PTP4A3 phosphatase mRNA is significantly elevated in a variety of cancer lineages." (PMID 34209460, 2021). "Other studies showed that overexpression of PTP4A3 promoted cancer cell proliferation." (PMID 32024182, 2020). "PTP4A3 overexpression promotes, and genetic deletion reduces, cancer cell migration." (PMID 29492190, 2018). "This region also contains some cancer related genes such as PTP4A3 and PTK2 genes." (PMID 27876019, 2016). "Ptp4a3 (commonly known as PRL-3) is an enigmatic member of the Ptp4a family of prenylated protein tyrosine phosphatases that are highly expressed in many human cancers." (PMID 23555575, 2013). "Ptp4a3 is traditionally classified as a gene associated with metastasis and not known to be involved in the early stages of cancer progression." (PMID 23555575, 2013). "The concept of therapeutically targeting Ptp4a3 could, therefore, be attractive at multiple stages of cancer." (PMID 23555575, 2013). "Dosage effects of PTP4A3 expression in relation to cellular responses may be more complex, particularly in cancer cells." (PMID 22028901, 2011). "This indicated that PTP4A3 might be a cancer-promoting gene in LIHC." (PMID 36213837, 2022). "PTP4A3 is the most frequently overexpressed PTP4A phosphatase in different cancer types, although some cancers also co‐express PTP4A1 and/or PTP4A2." (PMID 40657934, 2025). "PTP4A3/PRL-3 promotes a variety of oncogenic processes, including cell proliferation, invasion and cancer metastasis." (PMID 39883197, 2024). "There are other oncogenic genes located on 8q24, and one of these, Protein Tyrosine Phosphatase 4A3 (PTP4A3 also known as PRL-3), has gained some notoriety as being the most oncogenic phosphatase seen in human cancers." (PMID 34209460, 2021). "Because PTP4A3 controls cell migration, we interrogated the effect of JMS-053 on this cancer-relevant process." (PMID 34209460, 2021). "Therefore, PTP4A3 could be a potential target for cancer immunotherapy." (PMID 34630392, 2021). "PTP4A3/PRL-3 protein was mainly localized in the cytoplasm and nuclear membrane of the cancer cells, and rarely nuclear staining was also seen." (PMID 23064776, 2013). "The overexpression of PTP4A3/PRL-3 was significantly correlated with the serum levels of AFP and PIVKA-II, tumor vascular invasion, and advanced cancer stages in HCC patients." (PMID 23064776, 2013). "Some cancer-related genes are located in these highly common, early appearing RARs: MCL1, CTSK, ARNT, S100A10, PTK2, PTP4A3, and PSCA in the RAR-Gs; and DLC1, PINX1, and GATA4 in the RAR-Ls." (PMID 22938721, 2012).
cancer (continued). "In particular, we sought to understand how PTP4A3 regulates autophagy in HGSOC cells and whether targeting PTP4A3 in cancer cells that overexpress this protein sensitises them to chemotherapeutic drugs." (PMID 40657934, 2025). "PTP4A3 is overexpressed in 80.6% of randomly analysed human tumours of diverse cancer types, while absent in all examined normal tissues." (PMID 40657934, 2025). "Among these genes, PRL-3 (PTP4A3) was the most frequently overexpressed across cancer types, including colorectal, gastric, bladder, and breast cancers, consistent with previous studies linking PRL-3 to cancer progression." (PMID 40463094, 2025). "PRL3 or PTP4A3 is the most well-studied PRL and is highly expressed in several cancer types." (PMID 39050014, 2024). "The role of PTP4A3 in hematopoietic malignancies has not been studied as extensively as in carcinoma." (PMID 22028901, 2011). "The protein expression of PTP4A3/PRL-3 was significantly correlated with tumor differentiation (P < 0.0001), serum AFP (P = 0.0118), high serum PIVKA-II (P = 0.0214), hepatic vein invasion (P = 0.0374), tumor vascular invasion (P = 0.0198), and advanced cancer stages (P = 0.0047)." (PMID 23064776, 2013). "While definitive evidence is lacking, Ptp4a3 has been proposed to modulate multiple signaling pathways involving SRC, Rho GTPases, and PI3K-Akt in various forms of cancer." (PMID 23555575, 2013).